AQP1 (aquaporin 1 (Colton blood group))
Diseases named in the same sentence as AQP1 in open-access papers (continued):
Sharing a sentence is not in itself a finding about the gene and the disease.
tumor (continued). "Over-expression of AQP1 in tumour cell lines resulted not only in a predicted increase in cell membrane water permeability, but also a 2 to 3-fold accelerated migration rate of the AQP1-expressing tumour cells as compared to control cells in vitro." (PMID 26912239, 2016). "AQP1 facilitates movement of both endothelial cells and some tumour cells." (PMID 25821338, 2015). "We postulate that retained AQP1 expression in MM indicates a more differentiated phenotype of the tumour, with some retained expression of surface proteins, which could be exploited for therapy." (PMID 25821338, 2015). "AQP1 can be expressed by vascular endothelium as well as tumor cells, and blockade of AQP1 expressed by either cell types in the tumour may be beneficial." (PMID 25821338, 2015). "We postulated that higher AQP1 expression in these tumours may reflect better differentiation, since normal mesothelium expresses AQP1." (PMID 25821338, 2015). "We hypothesised that the retained expression of AQP1 in this tumour may offer treatment potential to AQP1-expressing tumours." (PMID 25821338, 2015). "The H226 cell line shows expression of AQP1 in >20% of tumour cells." (PMID 25821338, 2015). "Furthermore, in has been shown recently that aquaporins (in particular, AQP1) can be involved in migration of some tumor cells." (PMID 26098895, 2015). "Our in vitro results suggest that AQP1 blockade may be a useful strategy to limit MM tumour growth, but further in vivo work is required to fully evaluate the potential of AQP1 blockade to contribute to therapy in MM." (PMID 25821338, 2015). "Increased urinary levels of AQP1 were previously indicated to correlate with increased tumor size." (PMID 24803718, 2014). "Interestingly, targeted AQP1 gene disruption impairs angiogenesis and cell migration and AQP1-null mice show defective tumor angiogenesis resulting from impaired endothelial cell migration." (PMID 24338153, 2014). "It has been proposed that increased AQP1 expression in some human adenocarcinomas may be a consequence of angiogenesis and important for the formation or clearance of tumor edema." (PMID 24338153, 2014). "Although the small numbers prohibit reliable conclusions for the frequency of neoplasms in anti-AQP1-seropositive patients, they suggest that this frequency may be roughly similar with that of the anti-AQP4-seropositive patients." (PMID 24086369, 2013). "In clinical studies, AQP1 expression is correlated with tumor grade and poor prognosis." (PMID 23468877, 2013). "AQP1 deletion reduces endothelial cell migration, limiting tumour angiogenesis and growth." (PMID 21119880, 2010). "In this connection, AQP1 has been proposed as a novel promoter of tumor angiogenesis." (PMID 19584911, 2009). "Some exciting new studies are suggesting that AQP1 may have roles hitherto unsuspected – evidence has been obtained supporting a role for AQP1 in angiogenesis, particularly in wound healing, organ regeneration and possibly in tumour spread." (PMID 15888206, 2005). "Similarly, knocking out Aqp1 (which encodes a water channel protein; QTL Cia 6) expression revealed its fundamental role in cell migration—central to wound healing and tumour spread." (PMID 16254600, 2005). "Although the molecular mechanism of AQP1 in cancer biology is not fully understood, numerous studies have indicated that AQP1 is involved in the angiogenesis, migration, and proliferation of tumor cells, which plays an important role in the development of cancer." (PMID 37334171, 2023). "Moreover, the same group confirmed that tumor cell migration and metastasis were increased by AQP1 expression, whereas inhibition of AQP1 expression resulted in a significant reduction in the growth of new blood vessels in the commonly used chorioallantoic membrane (CAM) model." (PMID 35847914, 2022).
tumor (continued). "Although the current study showed correlations for AQP expression with ADCuh, ADCst or ADCslow, we still cannot infer that the AQP1 or AQP4 distribution in the tumor center might be denser than peritumor as the immunohistochemical results were only obtained for the solid tumor part." (PMID 34712604, 2021). "This could suggest that AQP1 is regulated by mechanisms within the hypoxic tumor microenvironment." (PMID 33644043, 2021). "AQP1 may play an essential role in the interface between tumor cells and their microenvironments." (PMID 32075009, 2020). "Moreover, AQP1 and AQP3 protein expression was highest in poorly differentiated tumors, whereas AQP5 is more expressed in moderately differentiated tumors, suggesting that AQPs are associated with tumor aggressiveness." (PMID 33178018, 2020). "Moreover, AQP-1, member of AQPs, is involved in cell migration, angiogenesis and tumor growth." (PMID 33209198, 2020). "Since AQP-1 could promote the rapid flow of water into the lamellar pseudopodia at the leading edge of migrating cells, thus promoting the change of cell morphology and the forward movement of tumor cells." (PMID 33209198, 2020). "Moreover, AQP1-KO perturbed tumor angiogenesis and led to reduced brain injury upon trauma." (PMID 31023968, 2019). "In addition, AQP1 deletion results in protection of brain trauma and a decreased tumor growth." (PMID 31023968, 2019). "Paradoxically, some manifestations in the AQP1-KO mice, e.g., hypotriglyceridemia, angiogenesis deficiency, and changed behavior of tumor, appeared to have no or little connection to water homeostasis at the first sight, and the mechanisms/pathways involved are far from current understanding." (PMID 31023968, 2019). "MMP2 is responsible for extracellular matrix (ECM) digestion and VEGF proteolytic release from the tumour matrix 26, 36; therefore, the reduced expression of MMP2 found in AQP1 KD tumours might also reduce the amount of the available VEGF necessary to induce a normal level of tumour angiogenesis." (PMID 29044946, 2018). "Although the mechanisms in which localization varies depending on ESCC cells are still unknown and require further investigation, the results of immunofluorescence analysis support our IHC analysis in which ESCC cells expressing AQP1 predominantly in the cytoplasm are involved in tumor progression." (PMID 30042826, 2018). "Hypoxia-induced glycolysis may enhance AQP1 expression in tumour cells to maintain their viability." (PMID 28146084, 2017). "Haematoxylin–eosin staining revealed no sign of necrosis in either the AQP1- or GFP-expressing tumours, indicating that the change in diffusion-weighted contrast in AQP1 xenografts is caused by AQP1 expression rather than necrosis or other changes in tumour morphology." (PMID 28008959, 2016). "To quantitatively evaluate whether AQP1 overexpression affects tumour growth in vivo, we measured growth curves and terminal tumour masses in subcutaneous xenografts established using the same cell lines as the intracranial tumours and induced the same way with doxycycline." (PMID 28008959, 2016). "If detectable levels of AQP1 are lacking in the urine of these patients, patients may elect for active surveillance of the tumor in the place of a nephrectomy or partial nephrectomy, and this surveillance protocol could include periodic assays for urinary AQP1." (PMID 24803718, 2014). "Moreover, AQP1 expression promotes tumor cell extravasation and metastasis." (PMID 23017148, 2012). "Therefore, AQP1 has been proposed as a novel promoter of tumor angiogenesis." (PMID 19584911, 2009). "Both survivin and AQPs, such as AQP1 and AQP5, are upregulated in response to hypoxic conditions in the tumor microenvironment, suggesting shared regulatory pathways, particularly via hypoxia-inducible factors (HIFs)." (PMID 40283503, 2025). "The spatial expression patterns of three key tumor stemness genes—REN, SFRP2, and AQP1—were examined in both tumor subtypes." (PMID 40534868, 2025).
tumor (continued). "This review focuses on the pivotal roles of aquaporins AQP1, AQP3 and AQP5 in tumor biology, emphasizing their significant contributions to cancer progression." (PMID 39941100, 2025). "Among the AQPs, AQP1, AQP3 and AQP5 have been consistently identified as being aberrantly expressed in various tumor types." (PMID 39941100, 2025). "This validation revealed cell type-specific expression patterns: SFRP2 was predominantly expressed in fibroblasts, AQP1 localized to proximal tubular cells, vasa recta, and bud-like epithelial cells, while REN was primarily expressed in tumor cells." (PMID 40534868, 2025). "Stimulating clues also derive from preliminary observations pointing to a beneficial effect of high AQP1 and AQP5 expression in subjects with biliary tract cancer, mainly in terms of longer survival, smaller tumor size, and depth of tumor invasion." (PMID 39596202, 2024). "Through analysis of the HPA database, we recognized remarkably higher expression levels of specific proteins, including AQP1, ITGA5, MAP3K8, PIK3R3, STC1, and TGM2, in HNSCC tumor tissues." (PMID 38688945, 2024). "The elevated expression of AQP1 and AQP3 not only stimulates tumor angiogenesis but also facilitates tumor proliferation and migration." (PMID 39440058, 2024). "In the context of NSCLC, the overexpression of AQP1, AQP3, AQP4, and AQP5 has been demonstrated to facilitate tumor angiogenesis, as well as the proliferation, migration, and invasiveness of tumor cells." (PMID 39440058, 2024). "Emerging evidence suggests a positive relationship between AQP1 and AQP4 expression and histological tumor grade and brain edema volume." (PMID 38476871, 2024). "The results suggest a positive correlation between the overexpression of AQP1 and AQP3 and the heightened proliferation and migration capabilities of tumor cells." (PMID 39440058, 2024). "This group also explored the impact of epigenetic modification on AQP1 expression, in which they performed chemical demethylation of A253 cells (derived from human SMG tumor) and saw increased expression of AQP1 through demethylation alone." (PMID 39225092, 2024). "While the observed differences lack statistical significance, we observed a gradual reduction in the expression of both AQP1 and AGTR2 as tumor progression advanced." (PMID 37991139, 2023). "The AQP1 expression, AQP3 expression and AQP5 expression were related to regional lymph node metastasis, histological grading, and tumor location of CRC, respectively." (PMID 37334171, 2023). "In the TCGA-HNSC cohort, we observed the expression of 12 ion channel genes in tumor and normal tissues; ANO1, AQP9, BEST2, CHRNA5, and KCNJ15 were upregulated in HNSCC, while AQP1, AQP5, SCNN1G, and SCN4A were downregulated." (PMID 36389709, 2022). "The expression of AQP1 can provide DWI image contrast, which makes it possible to image the gene expression of intracranial tumor xenografts." (PMID 35955578, 2022). "For colorectal cancer, the expression of AQP8 decreased, while that of AQP1, AQP3 and AQP5 increased, indicating that AQPs can be expressed in tumours in humans." (PMID 35178393, 2022). "Levels of AQP1 expressed in endothelial cells of peripheral blood vessels correlated with release of VEGF, resulting in angiogenesis and increased tumor growth in endometrial carcinoma." (PMID 33499000, 2021). "As both AQP1 accumulation and RIPK1 depletion coexist in TNBC, we first looked for a correlation between the expression profiles of them in the tumor samples detected by Western blotting." (PMID 33980862, 2021). "Tumor growth, VEGF signaling levels, vessel density, and lung metastases were reduced in AQP1 null mice compared to wild type." (PMID 33499000, 2021). "It was also noticed that the expression of AQP1 and AQP3 was increased in the advanced stage of cancer, the larger tumor, in patients with metastases, which correlates with the patient’s prognosis." (PMID 33271827, 2020).
tumor (continued). "AQP1, the membrane protein, was the first reported mammalian AQP and plays a significant role in tumor cell migration, proliferation and angiogenesis." (PMID 32782435, 2020). "Frozen tumor tissues and plasma were used to measure PBRM1, BAP1, SET domain-containing 2 (SETD2), KDM5C, FOXC2, CLIP4, AQP1, DDX11, BAIAP2L1, and TMEM38B mRNA levels, and correlation with the Fuhrman grade was investigated." (PMID 32392781, 2020). "We find here that the decrease of the tumor heat production is faster the higher the respective marker is expressed, suggesting that CAIX inhibition is more successful than AQP1 inhibition in this case." (PMID 31600976, 2019). "The common prognostic genes between AS event and genes included KRT222, LENG8, APOB, SLC3A1, SCD5, AQP1, and ADRA1A, which played roles in tumor biology." (PMID 31140607, 2019). "In conclusion, the results of the present study suggested that the cytoplasm dominant expression of AQP1 is related to a poor prognosis in patients with ESCC, and that it activates tumor progression by affecting Death receptor signaling pathway." (PMID 30042826, 2018). "Intratumoural injection of AQP1 siRNA and CTRL siRNA was performed 10 days after tumour cell implantation." (PMID 29044946, 2018). "Moreover, AQP1 could also be expressed in reactive astrocytes and the areas of tumor infiltration." (PMID 29245912, 2017). "Therefore, AQP1 water channel inhibition may be a novel approach to reduce tumor vessels." (PMID 27023529, 2016). "The AQP1 and GFP tumours proliferated at similar rates following doxycycline induction and reached statistically indistinguishable end-point masses (not significant P>0.5, n=4, pairwise t-test)." (PMID 28008959, 2016). "AQP1 and GFP expression in the bilateral tumours was confirmed by fluorescence imaging of fixed brain tissue slices." (PMID 28008959, 2016). "Finally, AQP1 is also expressed on some blood components and vascular endothelium, so some of the drug could have been bound here, preventing it from reaching therapeutic concentrations at the tumour cell level." (PMID 25821338, 2015). "Further studies investigated the distribution of AQP1 in tumors of the prostate, colon, lung, breast and ovary using TARP multi-tumor Tissue TMAs and CHTN (Cooperative Human Tissue Network) TMAs." (PMID 24338153, 2014). "Recent reports demonstrated that AQPs, particularly AQP1 and AQP5, are expressed in high grade tumor cells of a variety of tissue origins, and that AQPs are involved in cell migration and metastasis." (PMID 23468877, 2013). "In contrast,EC5 and EC6 subclasses exhibited conserved pro-angiogenic signatures encompassing established vascular morphogenesis regulators (CD34,AQP1) and emerging angiocrine signaling components (RAMP2/3,CRIP2,PCDH17),consistent with previous reports on tumor neovascularization dynamics." (PMID 41394809, 2025). "Conversely, SFRP2 and AQP1 were not confined to tumor regions, reaffirming their non-specific expression patterns observed in single-cell analysis." (PMID 40534868, 2025). "Moreover, in various cancers, AQPs such as AQP1, AQP3, and AQP5 exhibit correlated expression, reinforcing their significance in tumor progression." (PMID 40725460, 2025). "Downregulation of AEBP1 in tumour endothelial cells in vitro reduced levels of angiogenesis-related genes, POSTN and AQP1, suggesting that AEBP1 may regulate new blood vessel formation." (PMID 39930483, 2025). "Here, we attempted to identify potential regulators that could interfere with some degree of regulation of the disposition and function of AQP1 and AQP4 in tumor cells." (PMID 38476871, 2024). "AQP1+CD34-αSMA- objects were single, S100+ and CD45- cells and are likely tumor cells." (PMID 38361951, 2024). "We further showed that Aqp1 expression did not hinder the specific functions of different cells, such as phagocytosis, immune activation, and tumor cell migration, compared to GFP-expressing cell lines." (PMID 38649904, 2024).
tumor (continued). "The role of AQP1 in tumor cell proliferation is not as clearly defined as its roles in tumor cell migration and angiogenesis." (PMID 37762642, 2023). "Aquaporin 1 (AQP1) is also more abundant in cortical BM which is in line with several studies suggesting that aquaporins contribute to motility, invasiveness and edema formation and facilitate metabolism in tumor cells under hypoxic conditions." (PMID 38006431, 2023). "AQP1 knockdown in MDA-MB-231 inhibited proliferation, migration, invasion, and tumor growth." (PMID 36212456, 2022). "Moreover, expression of AQP1, AQP3, and AQP5 was found among tumor-infiltrating lymphocytes surrounding bronchogenic carcinoma cells." (PMID 35847914, 2022). "We found that AQP1 (5.83e−07), AQP2 (0.0146), AQP4 (0.000382), AQP6 (0.0221), AQP7 (0.00052), AQP9 (8.2e−07) had significant correlations with the pathological stages of the tumor." (PMID 35245343, 2022). "Gene expression analysis of AQP1, HIF-1α, HIF-2α, CXCR4, NMYC, NCAM mRNA reveals major differences between tumors but also between different areas of the same tumor, demonstrating great inter- and intra-tumor heterogeneity." (PMID 33467498, 2021). "The ADCslow at the center of the tumor showed a small negative correlation with AQP1, AQP4 and a moderate negative correlation with Ki-67 (p < 0.05)." (PMID 34712604, 2021). "First, we categorized clustered data into tumor and stromal populations using a panel of markers for each (epithelial: AQP1, AQP2, EPCAM; endothelial: PLVAP, CD31, CD34; fibroblast: PDGFRα, PDGFRβ; immune: CD45; tumor cell: CXCR4, VIM, KRT18, PAX8, PAX2, CA9, CD10)." (PMID 34884982, 2021). "The correlation analysis between DWI-derived imaging parameters and histological indices revealed that expression of AQP1, AQP4 and Ki67 were correlated with ADCst, f, ADCslow and ADCuh at the center of the tumor while had little correlation with those of peritumoral imaging parameters." (PMID 34712604, 2021). "Immunofluorescence staining of AQP1, CXCR4 and MAP2 of the primary tumor revealed AQP1 expression in some but not all tumor areas, as well as staining of vascular structures in which AQP1 occurs physiologically." (PMID 33671521, 2021). "The ADCst at the center of the tumor showed a small negative correlation with AQP1, AQP4 and Ki67 (p < 0.05)." (PMID 34712604, 2021). "The ADCst, ADCslow and ADCuh at tumor center presented correlations with AQP1 and AQP4 while AQP9 did not correlate with any DWI metric." (PMID 34712604, 2021). "The f coefficient at the center of the tumor showed a small negative correlation with AQP1 and Ki67 (p < 0.05)." (PMID 34712604, 2021). "In addition, we showed that only SRg3 blocks the water transport function of aquaporin 1 (AQP1), a protein that plays important roles in angiogenesis, tumour growth, and metastasis." (PMID 34066403, 2021). "Meanwhile, a significant negative correlation between AQP1 and miR-3194-3p expressions in tumor tissues from 30 BC patients is revealed." (PMID 32903818, 2020). "AQP1 is upregulated from early through late stages of colorectal carcinogenesis, and expression levels have been suggested to correlate with tumor invasiveness, prompting classification of AQP1 as a negative prognostic indicator of patient survival." (PMID 32679804, 2020). "Statistical analysis of AQP1 expression was not performed because of its absence in MEC tumor cells." (PMID 32075009, 2020). "We found that AQP1 was expressed by GBM tumor cells, but these AQP1‐positive tumor cells did not co‐express THSD7A." (PMID 32253832, 2020). "We assigned a grade based on the proportion of tumor cells expressing AQP1 in each specimen: 0 (none), 1 (<5%), 2 (5%‐50%), 3 (50%‐75%), and 4 (>75%)." (PMID 32253832, 2020). "Immunostaining showed that AQP1 was mostly expressed in the cells of the fibrovascular septae, but not in the tumor cell nests." (PMID 31600976, 2019).